CRP (C-reactive protein)
Diseases named in the same sentence as CRP in open-access papers (continued):
Sharing a sentence is not in itself a finding about the gene and the disease.
COVID-19 (continued). "In patients without a history of COVID-19 (Group 2), statistically significant associations with FMD were observed only for ESR, fibrinogen, CRP, and D-dimer levels." (PMID 40143236, 2025). "Further investigation through laboratory analysis revealed a white blood cell (WBC) count of 6.6, an elevated C-reactive protein (CRP) level of 33, a urea level of 10, negative blood cultures, and positive results on COVID-19 antigen and PCR tests." (PMID 40065896, 2025). "After his COVID-19 symptoms were resolved, he began experiencing abdominal discomfort, accompanied by an elevated white blood cell (WBC) count of 8.5 × 109/L and a C-reactive protein (CRP) level of 7.47 mg/dL." (PMID 40909060, 2025). "The C-reactive protein (CRP), neutrophil count (NE), neutrophil-to-lymphocyte ratio (NLR), platelet-to-lymphocyte ratio (PLR) were significantly higher in the severe COVID-19 group, while lymphocyte count (LY) and eosinophil count (EO) were significantly lower in the non-severe group (p < 0.001)." (PMID 40861215, 2025). "CRP, D-dimer, fibrinogen, ferritin, and LDH were elevated with COVID-19 severity." (PMID 40087795, 2025). "According to our findings, among patients with moderate/severe COVID-19, besides decreased FVIII activity, higher CRP levels, prolonged APTT, decreased functional plasminogen activity, and markedly reduced FXIII levels were observed compared to those with asymptomatic/mild disease." (PMID 40303405, 2025). "Not only other cytokines, e.g., tumor necrosis factor-alpha, but also white blood cells have shown correlations with CRP, underscoring that CRP elevation in COVID-19 reflects a broader pro-inflammatory milieu rather than the action of IL6 alone." (PMID 41373577, 2025). "This study found that CRP levels in ICU patients were significantly higher than those in non-ICU patients, indicating that CRP, as an acute-phase inflammatory marker, can reflect the inflammatory activation state in COVID-19 patients." (PMID 40444276, 2025). "We observed higher levels of bilirubin, D-dimer, C-reactive protein, urea, and plasmatic cytokines, such as IL-1β, IL-6, IL-8, IL-10, IL-17A, IL-23, TNF-α, and IFN-α in individuals with the critical form of acute COVID-19 compared to individuals with the severe and/or moderate WHO clinical forms." (PMID 39861879, 2025). "Elevated ferritin levels were observed in both COVID-19 and non-COVID-19 patients with thrombosis, and these levels appeared to correlate with inflammatory markers, such as CRP and IL-6, and coagulation markers, including fibrinogen." (PMID 40364223, 2025). "The level of CRP was significantly reduced by adding CHM in the early stage of COVID-19(MD = 2.56, 95%CI [1.28,3.83]; P <0.01; I2 = 14%), while no statistical differences were identified at the later stage (MD = 0.90, 95%CI [-6.28, 8.08]; P = 0.81; I2 = 83%)." (PMID 39946361, 2025). "COVID-19 patients had significantly higher levels of thrombospondins than healthy controls and were positively correlated with inflammatory markers, including ESR, CRP, PCT, ferritin, and biochemical parameters." (PMID 40076669, 2025). "Previously, a negative correlation between C-reactive protein, neutrophil-to-lymphocyte ratio, and telomere length in patients with COVID-19 was also described." (PMID 40950970, 2025). "The increased CRP together with elevated IL-6 and IL-15 in PLWH/COVID-19 could indicate hyperinflammation, further explaining the observed differences in the outcome of the COVID-19." (PMID 41516165, 2025). "The C-reactive protein (CRP)-to-lymphocyte ratio (CLR) is an emerging inflammation-based biomarker that has demonstrated prognostic value in various conditions, including malignancies, COVID-19, and acute pancreatitis." (PMID 40988967, 2025). "Post-COVID coagulation studies and inflammatory markers (CRP, D-dimer, IL-6) were not obtained as the decision for palliative care was made within 24 hours of COVID-19 diagnosis due to catastrophic neurological deterioration." (PMID 41503306, 2025).
COVID-19 (continued). "In this direction, newer indices such as the C-reactive protein-to-lymphocyte ratio (CLR) have been proposed, with one single-center study showing that elevated CLR, together with higher CRP and D-dimer, strongly predicted PE and mortality in COVID-19." (PMID 41463074, 2025). "It will encompass an investigation into symptoms, laboratory and imaging findings (including chest X-rays, CT scans, C-reactive protein levels and complete blood counts) and spirometry data concerning COPD outcomes (recovery, complications and mortality) in relation to COVID-19." (PMID 39360405, 2025). "The multivariable logistic regression demonstrated that urea, CRP, and LDH showed significant positive relationships (p < 0.001) with the severity of clinical outcome both generally and in COVID-19 male patients, as well as LDH in COVID-19 female patients." (PMID 40868247, 2025). "Regarding inflammation biomarkers, testosterone is inversely associated with interleukin-6 (IL-6) and C-reactive protein (CRP) in severe COVID-19, while testosterone and estradiol are similar in women with and without severe COVID-19." (PMID 40868247, 2025). "A study by Hajibeygi et al37 that was conducted on non-ICU patients with COVID-19 demonstrated that a mixture of TIM can reduce CRP levels meaningfully in 5 days." (PMID 40980426, 2025). "Multivariate regression models that compare COVID-19 and influenza in predicting intensive care unit admission, need for CPAP, or intubation were envisaged, adjusting for the following confounders: sex, ACCI, CRP, creatinine, LDH, and NLR." (PMID 40871340, 2025). "In addition, the elevated levels of CRP and LDH in this group indicate heightened inflammatory responses and potential tissue damage, both of which are characteristic of severe COVID-19." (PMID 40756075, 2025). "The exact pathophysiology of elevated C-reactive protein in these MOGAD patients with syphilis, HIV, or COVID-19 remains unclear." (PMID 40766314, 2025). "The level of CRP was elevated in the SC group compared to the non-SC group in our study, which was consistent with previous findings in COVID-19 studies." (PMID 40861215, 2025). "Median CRP levels were higher in COVID-19 patients with PE than those without PA (135.5 vs. 95.7 mg/L)." (PMID 40647684, 2025). "Numerousstudies have corroborated the inflammatory profile of COVID-19, with serum levels ofpro-inflammatory biomarkers, including LDH, CRP, D-dimer, and IL-6, beingsignificantly elevated upon admission in both critical and non-critical patientsacross multiple clinical trials." (PMID 40532042, 2025). "After adjusting for potential confounding variables, found a nonlinear relationship between hs-CRP levels and 10-year CVD risk progression in T2DM patients infected with COVID-19 (P-overall<0.001, P-nonlinear=0.014)." (PMID 40933377, 2025). "Among these, elevated levels of IL-6, CRP, and tumor necrosis factor alpha (TNFα) for one or more months after SARS-CoV-2 infection were indicators that patients may experience long-COVID-19 symptoms." (PMID 39859366, 2025). "Inflammatory markers (C-reactive protein (CRP) and procalcitonin) and more nuanced indicators like the neutrophil-to-lymphocyte ratio (NLR) and systemic immune inflammation index (SII) can offer a window into infection severity in COVID-19 patients." (PMID 40299432, 2025). "Besides, positive associations between serum transgelin with interleukin-6 (IL-6), CRP, D-Dimer, and lactate dehydrogenase (LDH) were observed among COVID-19 patients." (PMID 39676863, 2024). "Additionally, pro-inflammatory markers like high C-reactive protein (CRP), procalcitonin, and ferritin are commonly elevated in individuals with both COVID-19 and diabetes." (PMID 39338165, 2024). "CRP, LDH and Ferritin levels increased in severe COVID-19 patients." (PMID 38245638, 2024).
COVID-19 (continued). "For the glucose level, the area under the ROC curve for AUC was 0.649, CI [0.612; 0.685]; for creatinine it was 0.581, CI [0.543; 0.618]; for CRP it was 0.600, CI [0.562; 0.637]; for LDL it was 0.542, CI [0.504; 0.581]; and for previous COVID-19 it was 0.558, CI [0.519; 0.596]." (PMID 39451585, 2024). "Quercetin effectively reduced COVID-19 markers (serum ALP, q-CRP, LDH) in severe cases." (PMID 39434894, 2024). "CoQ10 is also a potent anti-inflammatory agent that effectively down-regulates cytokines (i.e., TNF-α, IL- 6, CRP) and could optimize viral-disrupted ACE2/RAAS system, by exerting anti-angiotensin II effects and decreasing OxS in COVID-19 patients." (PMID 38555403, 2024). "In one study, participants with COVID-19 and depression had greater CRP levels than those with COVID-19 without current major depressive disorder." (PMID 39408010, 2024). "More importantly, as compared to NLR, SII, NLPR, CRP, and procalcitonin, NPR may be the most effective inflammatory indicator to predict the probability of AKI in severe COVID-19 patients." (PMID 39465828, 2024). "High CRP levels in COVID-19 patients, normally lacking in other viral infections, can be caused by Macrophage Activating Syndrome." (PMID 38398063, 2024). "Therefore, the present study aims to examine the relationship between inflammatory markers such as CRP, ESR, LDH, D-dimer, ferritin, and PCT and the characteristics of disease progression and outcomes in individuals affected by COVID-19." (PMID 39195007, 2024). "With regard to the AUC-ROC analysis, parameters such as SpO2, CRP, ALT, AST, and D-dimer levels exhibited good discriminatory power between co-infected and COVID-19 patients alone, while others like IL-6 and lymphocyte count showed higher sensitivity but lower specificity." (PMID 38793006, 2024). "Serum S100A12 did not correlate with CRP, procalcitonin and interleukin-6 levels in the serum of patients with moderate and severe COVID-19." (PMID 39066246, 2024). "Because HM and recent chemotherapy have been associated with poor outcomes among patients with cancer and COVID-19, the anti-inflammatory effects of nirmatrelvir-ritonavir and azvudine were determined via the expression levels of IL-6, PCT, CRP, and various serological laboratory indicators." (PMID 39059144, 2024). "Thus, CRP, LDH and glucose can be considered important predictors in evaluating patients with COVID-19 (AUC > 0.7)." (PMID 38392603, 2024). "As expected, CRP was substantially higher in unhealthy samples (COVID-19 positive and negative) relative to healthy individuals." (PMID 38879593, 2024). "Omicron-infected COVID-19 patients exhibited significantly elevated systemic inflammatory markers, including CRP, IL-6, LDH, and ferritin, which showed negative correlations with SOD activity." (PMID 38464514, 2024). "Participants with PASC displayed significantly higher concentrations of pro-inflammatory CRP at 21–24 weeks after COVID-19 onset compared to those without PASC." (PMID 39008486, 2024). "In candidemia patients with COVID-19; higher procalcitonin, lactate, CRP, NLR, urea, and lower LCR were found in non-survivors than survivors." (PMID 38545189, 2024). "We found that a positive correlation was between neopterin and CRP levels (r = 0.485, P < .001), while a negative correlation was between neopterin and albumin levels in patients with severe COVID-19 (r = 0.669, P < .001)." (PMID 39058886, 2024). "For clinical decision-making, it is recommended to use mainly biochemical markers such as elevated levels of D-dimer, CRP, LDH, troponin, ferritin, and CK, as well as a decrease in absolute lymphocyte counts and an increase of NLR, as indicators of COVID-19 severity." (PMID 38500972, 2024).
COVID-19 (continued). "It has been shown that some parameters related to inflammation, such as TNFα, IL-6, interleukin-8 (IL-8), interleukin-10 (IL-10), CRP, white blood cell count (WBC), lymphocyte count (LC), and the number of neutrophils (NC) are correlated with the severity of COVID-19." (PMID 39335569, 2024). "Serum proteins like C-reactive protein, ferritin, D-dimer, procalcitonin, interleukin-6, serum creatinine, ALT, and AST remain to be promising tools for monitoring the prognosis and predicting the complications of COVID-19." (PMID 38378528, 2024). "All three (CRP, LDH, and NLR) are known COVID-19 biomarkers." (PMID 38476940, 2024). "Moreover, as a treatment for post-COVID-19 condition, VOR has shown significant cognitive improvement in patients with elevated CRP levels, which further supports VOR’s anti-inflammatory effects." (PMID 39575195, 2024). "In fact, a recent study reported CRP to be the best at discriminating between severe and non-severe COVID-19 compared to various other hyperinflammatory biomarkers." (PMID 39402606, 2024). "This is also true for CRP and procalcitonin, which do not increase further in COVID-19 patients with bacterial co-infection." (PMID 38255230, 2024). "Many biochemical parameters (eg, elevated CRP, thrombocytopenia, and an elevated ferritin level) are poor prognostic factors in COVID-19, and they have not been used to define disease severity per the current literature." (PMID 39625772, 2024). "Additionally, a recent study confirmed that a COVID-19 group of psychiatric patients had higher NLR, ferritin, and CRP levels than those of their control group." (PMID 39408010, 2024). "Elevated CRP, ferritin, and NLR levels were consistently observed in positive cases, while albumin levels were lower, aligning with known clinical characteristics of COVID-19." (PMID 39767161, 2024). "Similarly, clinical biomarkers like IL-6, CRP, LDH, and D-Di have been identified as predictors of disease progression and treatment outcomes in COVID-19." (PMID 39712749, 2024). "The CRP concentration of participants in the VCO also normalized at day 14, which is 11 days faster than the control group; this result is consistent with the resolution of their COVID-19 symptoms." (PMID 38282651, 2024). "Blood chemistry showed that hospitalized patients who did not survive COVID-19 had elevated levels of triglycerides, creatinine, blood urea nitrogen, C-reactive protein, and procalcitonin compared to those who recovered but without statistical differences." (PMID 38673053, 2024). "Our results demonstrated higher WBC and CRP (p=0.005) and lower lymphocyte count in hospitalized COVID-19 pregnant patients compared to the nonhospitalized ones." (PMID 39659767, 2024). "Independent samples t-test was used to compare the anti-SARS-CoV-2 IgG, IL-6, and CRP levels between the participants with and without post-COVID-19 symptoms." (PMID 39056056, 2024). "Based on these results, we believe that classic inflammation markers such as CRP are not sufficient for stratification on COVID-19 patients." (PMID 38813381, 2024). "In fact, among the fourteen serological biomarkers that we analyzed, CRP, which has been commonly investigated in COVID-19, was not included, since the routine assessment of these patients in our pulmonary fibrosis unit did not collect it." (PMID 39204242, 2024). "This means that among biomarkers, elevated levels of CRP, serum ferritin, and IL-6 were significant in patients with COVID-19 and renal injury compared to patients without renal involvement." (PMID 38975470, 2024). "In addition, children with severe COVID-19 tended to have elevated levels of LDH, CRP, PCT, D-dimer and serum ferritin, similar to what has been reported in adult patients with COVID-19." (PMID 39596272, 2024).
COVID-19 (continued). "The severe COVID-19 patients were older, had significantly more comorbidities, and significantly higher neutrophil/lymphocyte ratio, C-reactive protein, and interleukin-6 than the non-severe COVID-19 patients (all p < 0.05)." (PMID 38504259, 2024). "There was no consensus on cut-off values from the studies reporting CRP, and furthermore, there are several confounding issues with COVID-19, inflammation and CRP." (PMID 39290622, 2024). "In addition, CRP correlated well with levels of DNA and NET degradation activity in COVID-19 patient plasma suggesting a link between CRP and the capacity to degrade cell free -DNA in the circulation." (PMID 39009040, 2024). "Markers such as CRP, AST, basophils and lymphocytes push the predictions towards severe COVID-19." (PMID 38245638, 2024). "Studies revealed several laboratory markers and indices such as C-reactive protein (CRP), Lactate dehydrogenase (LDH), high-sensitivity cardiac troponin I (hs-cTnI), lipid ratios, triglyceride to glucose index (TyG) can predict the prognosis of COVID-19." (PMID 39334249, 2024). "The role of serological components in causing cardiovascular damage in COVID-19 is further corroborated by a significant negative correlation of IL-6, TNF-α, IL-1β, IL-10, and CRP levels with cardiomyocyte viability." (PMID 38041432, 2024). "Our study results reflected quite the opposite, with similar CRP levels among our three groups and higher leucocyte values in the COVID-19-negative and unvaccinated groups." (PMID 39458089, 2024). "In a study involving 200 T2DM subjects with COVID-19 infection, the expressions of CRP were highly increased compared to non-DM patients with COVID-19." (PMID 38675414, 2024). "Another limitation of this study was only focused on symptomatic and asymptomatic COVID-19, and this study only did subgroup analysis in symptomatic group (CRP levels between severe and nonsevere group)." (PMID 38905361, 2024). "The secondary endpoints (CRP, Ang-2, and suPAR elevation and a higher incidence of AKI) might even suggest an undesired impact of sevoflurane in patients with COVID-19-related lung injury." (PMID 38536545, 2024). "We found that the CRP values are higher in the group with COVID-19 compared to the NonCOVID-19 group, regardless of the age of the subjects." (PMID 38672258, 2024). "CRP-levels were elevated (> 5 mg/l) at baseline in COVID-19 (9/13 patients (69%)), and non-COVID-19 (9/15 patients (60%)) group, and partly on discharge (COVID-19: 5/15 (33%), Non-COVID-19: 8/12 (67%))." (PMID 39438985, 2024). "This can be illustrated by the relatively late spike of C-reactive protein and neutrophils, without any obvious super infection, among intubated COVID-19 patients." (PMID 38892098, 2024). "Therefore, our study was aimed to investigate the changes in circulating levels of arachidonic acid, IL-6, and CRP in patients with FluA, RSV, or COVID-19, and to analyze the potential of these parameters as diagnosis of prognosis biomarkers." (PMID 39066228, 2024). "Plasma PCSK9 levels of the COVID-19 patients did not correlate with C-reactive protein (CRP), procalcitonin, IL-6, ferritin, or leukocyte count, illustrating that, at least in SARS-CoV-2 infection, higher PCSK9 is not simply a marker of inflammation." (PMID 39051245, 2024). "The levels of ferritin, CRP, and D-dimer have been reported to be 1.75, 10.7, and 2.4 times higher in COVID-19 non-survivors." (PMID 38610151, 2024). "Another study examined clinical features and lab indicators in severe and non-severe COVID-19 patients, identifying significant differences in neutrophil-to-lymphocyte ratio, C-reactive protein, and lactate dehydrogenase." (PMID 39273719, 2024). "A study conducted in Spain found that PLWH well-controlled on ART admitted with COVID-19, despite being older, had lower serum CRP levels than those living without HIV with COVID-19." (PMID 39597537, 2024).